IFNG (interferon gamma)
Diseases named in the same sentence as IFNG in open-access papers (continued):
Sharing a sentence is not in itself a finding about the gene and the disease.
genital warts (5 papers, 2015 to 2025). "The increased expression of GZMB, IFNG, IL-12B, and IL-8 and the decreased expression of NFATC4 and IL-7 in genital wart samples were highlighted." (PMID 40142865, 2025). "The involvement of T helper 1 (Th1) cells in host defense against HPV was evidenced in this study by the overexpression of CD4, along with overexpression of IFNG, IL12B, and IL8 in genital warts." (PMID 37053156, 2023). "We investigated the role of interleukin-4 (IL-4) and interferon-gamma (IFN-γ) as ex vivo immunologic predictors to estimate the response to the bivalent HPV vaccine as a potential immunotherapy for cutaneous and anogenital warts." (PMID 34835211, 2021).
hip fracture (5 papers, 2014 to 2023). Traumatic or pathological injury to the hip in which the continuity of either the femoral head, femoral neck, intertrochanteric or subtrochanteric regions is broken. "Candidate mediators, where current literature supports both an association with concentration of serum trp and hip fracture risk, include circulating interferon gamma cytokine levels and amount of ingested antioxidants." (PMID 37808397, 2023).
insomnia (5 papers, 2017 to 2026). A sleep disorder characterized by difficulty in falling asleep and/or remaining asleep. "We found that interferon-gamma response, allograft rejection, and apical junction were markedly enriched in the insomnia group." (PMID 35958162, 2022).
intestinal tumors (5 papers, 2020 to 2024). "GW501516 treatment significantly decreased CD8+ T -cell proliferation and IFNγ-expressing CD8+ T cells in intestinal tumors and matched normal tissues compared with the control group, suggesting PPARδ regulates CD8+ T-cell activation." (PMID 39292167, 2024). "Our results demonstrated that the innate IL-25-ILC2 axis supports intestinal tumor progression in part through promoting MDSCs and suppressing anti-tumoral T cells and IFNγ." (PMID 35658010, 2022). "S3E), both known producers of IFNγ, which can inhibit intestinal tumors." (PMID 35658010, 2022).
Japanese encephalitis (5 papers, 2017 to 2021). A disease due to a virus transmitted by an arthropod). "Moreover, IFNγ was pathogenic in a murine model of Japanese encephalitis by causing blood-brain barrier disruption." (PMID 28330482, 2017). "Populations of innate and adaptive lymphocytes, which participate in related arboviral infections such as West Nile and Japanese Encephalitis, could be modulated by IFNγ and somewhat participate in early disease pathogenesis." (PMID 33410731, 2021).
kidney transplant (5 papers, 2013 to 2024). A surgical procedure in which one or both kidneys from a donor are implanted into a recipient. "In addition a recently published study by Chavarot and colleagues evaluated the IFNγ T-cell responses after two injections of an mRNA vaccine in kidney transplant recipients treated with belatacept." (PMID 33923063, 2021). "Here, we studied the methylation of two mediators of the immune response: the pro-inflammatory cytokine interferon γ (IFNγ) and the inhibitory receptor programmed death 1 (PD1) in naïve and memory CD8+ T cell subsets in kidney transplant recipients receiving immunosuppressive medication." (PMID 27891189, 2016).
lymphedema (5 papers, 2009 to 2025). Excess fluid collection in tissues, causing swelling. "Lymphedematous skin from clinical biopsy specimens and mouse models of lymphedema are infiltrated with large numbers of CD4+ cells that co-express interferon gamma (IFN-γ; putative Th1 cells) and CD4+ cells that co-express interleukin 4 (IL4) or IL13 (putative Th2 cells)." (PMID 30936872, 2019).
metastatic prostate carcinoma (5 papers, 2020 to 2026). A carcinoma that arises from the prostate gland and has spread to other anatomic sites. "Longitudinal biopsy analysis in metastatic prostate cancer showed that AR inhibition enhanced immune cell and IFNγ signatures." (PMID 41486951, 2026). "Furthermore, in mouse models of metastatic prostate cancer, IFNG-treated xenografts exhibited significantly smaller tumor volumes than untreated counterparts." (PMID 38287309, 2024).
neuritis (5 papers, 2017 to 2025). A neuropathy arising from inflammation of one or more nerves. "In fact, in an in vitro co-culture model with macrophages and neurons, phagocytes infected with T. cruzi and stimulated only with IFNγ induced neuronal death and neuritis by producing NO via iNOS." (PMID 33561140, 2021).
retinal degeneration (5 papers, 2010 to 2024). Degeneration of the retina. "Moreover, IFNγ is also reported to increase the expression of reactive oxygen species, which has been implicated in ocular inflammation and retinal degeneration." (PMID 20157617, 2010). "Further investigations are required to elucidate the mechanisms by which IL-18 may have a role in regulating inflammation in retinal degenerations, including through the induction of interferon-gamma (IFN-γ), a cytokine thought to play a role in AMD." (PMID 31379825, 2019). "Importantly, we show that glycolysis in inflammatory M(LPS + IFNγ) microglia also relays on GLUT1-mediated glucose uptake, and blocking GLUT1 re-programmed proinflammatory microglia from glycolysis to OXPHOX, suppressed microglial activation and reduced light-induced retinal degeneration." (PMID 30634998, 2019).
sclerosing cholangitis (5 papers, 2020 to 2024). A chronic, autoimmune inflammatory liver disorder characterized by narrowing and scarring of the lumen of the bile ducts. "The CD8+ cells associate with sclerosing cholangitis by producing interferon gamma." (PMID 34046801, 2021).
smallpox (5 papers, 2003 to 2024). A condition that is caused by infection with Variola, and that is characterized by small, raised bumps. "An overlapping peptide library of four vaccinia membrane proteins known to induce an immune response in vaccinated individuals was synthesized and tested in IFNγ ELISPOT assays using the PBMCs of 29 recent smallpox vaccine recipients." (PMID 32318055, 2020).
soft tissue sarcoma (5 papers, 2019 to 2025). A malignant neoplasm arising from muscle tissue, adipose tissue, blood vessels, fibrous tissue, or other supportive tissues excluding the bones. "Another study showed that the double homeobox 4 (DUX4) protein is expressed in a wide range of adult solid cancers, including soft-tissue sarcomas, and blocks IFNγ-mediated MHC class I induction in tumor cell lines and immortalized myoblasts." (PMID 38318504, 2023).
streptococcal infection (5 papers, 2017 to 2024). Any of the several infectious disorders caused by members of streptococcus, a genus of gram positive bacteria belonging to the family Streptococcaceae. "In fact, it has been shown that IL-18 can protect from Streptococcal infections independently of IFNγ." (PMID 29791511, 2018).
Tumor Lysis Syndrome (5 papers, 2017 to 2022). a group of metabolic abnormalities that can occur as a complication during the treatment of cancer, most commonly after the treatment of lymphomas and leukemias. "In the PDX-2 experiment, administration of UCART123 to mice with high tumor burden caused a burst of IFNγ secretion and rapid demise of animals, possibly from cytokine release and/or tumor lysis syndromes." (PMID 35484100, 2022). "Interestingly, Pt #17 showed low levels of IFNG, IL6, IL1B, C-reactive protein (CRP) and Ferritin, suggesting the grade 3 CRS might be attributed to tumor lysis syndrome or other inflammation pathways." (PMID 34518515, 2021).
viral meningitis (5 papers, 2015 to 2022). Inflammation of the membranes surrounding the brain and spinal cord due to a viral infection. "Both, bacterial and viral meningitis additionally displayed significantly elevated concentrations of the cytokines CCL1, CCL19, CCL20, CXCL2, CXCL6, IFNγ, and IL16." (PMID 31727097, 2019). "Similar to other, non-specified forms of viral meningitis, we observed IFNγ and chemokine elevations in the CSF." (PMID 35788177, 2022). "Also, in viral meningitis, multiple cytokines (16/36) were elevated and we could confirm previously reported results for CXCL9, CXCL11, and IFNγ." (PMID 31727097, 2019).
xerostomia (5 papers, 2011 to 2025). Dryness of the mouth resulting from reduced salivary secretion. "Radiation induced xerostomia patients are already being treated with MSC(BM) pre-licensed with IFNγ." (PMID 41323369, 2025). "A pilot study with IFNγ-stimulated MSCs in the submandibular gland of patients with radiation-induced xerostomia was well tolerated, and some patients experienced an increase in saliva production." (PMID 38543329, 2024). "Our data support that MSC(SG) treated with IFNγ and TNFα could serve as a therapeutic tool to treat radiation-induced xerostomia." (PMID 41323369, 2025). "Our objective is to compare MSC(SG) to more traditional MSC sources including MSC(AD) and MSC(BM), evaluating the effects of cytokine stimulation (IFNγ and TNFα) on the trophic secretome and function of MSC(SG) in the treatment of radiation-induced xerostomia." (PMID 41323369, 2025).
adrenocortical carcinoma (4 papers, 2007 to 2025). "Furthermore, IFNγ enhanced erastin-induced ferroptosis, increasing lipid peroxidation, iron, mitochondrial damage, and ROS in adrenocortical carcinoma cells." (PMID 38539832, 2024). "Accordingly, IFNγ treatments failed to increase lipid peroxidation and mitochondrial damage in adrenocortical carcinoma cells with SLC7A11 over-expressed or STAT1 inhibited." (PMID 38539832, 2024).
Amebic colitis (4 papers, 2011 to 2019). "Moreover, T cell derived IFNγ and IL-17 were also essential for protection against intestinal amoebiasis in a murine model vaccinated with recombinant LecA fragment of the Gal-lectin, determined by adoptive T cell transfer and IFNγ/Il-17 neutralizing assays." (PMID 26090442, 2015).
ANCA-associated vasculitis (4 papers, 2017 to 2021). "CD8+ T cells have a pathogenic role in ANCA-associated vasculitis, since they can produce both IFNγ and tumor necrosis factor." (PMID 28626447, 2017). "TH1 lymphocytes and IFNγ stimulate macrophage recruitment in SLE- and ANCA-associated vasculitis, as well as anti-GBM nephropathy in experimental models." (PMID 28626447, 2017).
autoimmune gastritis (4 papers, 2021 to 2023). Inflammation of the body fundic mucosa of the stomach. "Among these, T helper 1 (Th1) cells secrete the pro-inflammatory cytokine interferon-gamma (IFN-γ), which contributes to the destruction of parietal cells and plays a critical role in the pathogenesis of autoimmune gastritis." (PMID 37504250, 2023).
bone cancer (4 papers, 2016 to 2023). A primary or metastatic malignant neoplasm affecting the bone or articular cartilage. "The top upstream regulators in the bone cancer pain model are shown inFigure 8A (p-value of overlap <0.05, ANOVA) and includes cytokine IFNG (activation z-score 1.9); growth factor LEP (activation z-score 0.4); and transcription regulator NFE2L2 (activation z-score 1.9)." (PMID 30079380, 2018).
colorectal adenoma (4 papers, 2010 to 2024). An adenoma that arises from the colon or rectum. "The aims of this study were to examine whether serum concentrations of IL-1β, IL-2, IL-8, IL-10, IL-12p70, GMCSF, IFNγ, and TNFα were associated with flavonol intake or could predict colorectal adenoma recurrence." (PMID 20924374, 2010). "Research has shown that SOX17 enables immune evasion in early colorectal adenomas and cancers by suppressing interferon-gamma (IFNγ) signaling, thereby reducing the immunogenicity of tumor cells." (PMID 38981872, 2024). "In the current study, we examined serum concentrations of eight cytokines (IL-1β, IL-2, IL-8, IL-10, IL-12p70, GMCSF, IFNγ, and TNFα) in relation to flavonol intake and colorectal adenoma recurrence and found none to be associated with flavonol intake and with colorectal adenoma recurrence." (PMID 20924374, 2010).
endophthalmitis (4 papers, 2018 to 2025). An infectious process affecting the internal structures of the eye. "While the role of certain immune mediators like tumor necrosis factor alpha (TNF-α) and interferon gamma (IFN-γ), have been studied in the development of endophthalmitis in animal models, very few expression studies have been carried out in humans suffering from infectious endophthalmitis." (PMID 30296277, 2018).
gastric MALT lymphoma (4 papers, 2019 to 2024). "Those that cause persistent inflammatory irritation include CagY (the Helicobacter pylori (H. pylori) CagY Protein), and it predominantly drives interferon-gamma (IFN-γ) and interleukin-17 (IL-17) secretion by gastric CD4+ T cells in H. pylori-infected patients with low-grade gastric MALT lymphoma." (PMID 40729186, 2023). "In the murine model of Helicobacter felis (H. felis)-induced gastric MALT lymphoma, tumor-infiltrating CD4+ T cells co-express surface markers CD28 and CD69, and produce large quantities of IL-4, but not of interferon-gamma (INF-γ)." (PMID 30999581, 2019).
gonococcal infection (4 papers, 2018 to 2025). "Accordingly, local genital administration of IL-12 encapsulated in sustained-release microparticles during gonococcal infection induced Th1-dependent immune responses with the production of IFNγ by CD4+ T cells and anti-gonococcal antibodies, and accelerated clearance of the infection." (PMID 31681305, 2019).
gram-negative bacterial infections (4 papers, 2011 to 2023). Infections caused by bacteria that show up as pink (negative) when treated by the gram-staining method. "During gram-negative bacterial infection where TLR signalling is activated, the production of interferon gamma (IFN-γ) by Th1 cells primes and potentiates macrophage activation and increases microbicidal functions." (PMID 36744644, 2023).
Guillain-Barre syndrome (4 papers, 2019 to 2024). A spectrum of rare post-infectious neuropathies that usually occur in otherwise healthy patients. "Another study demonstrated a correlation between decreased DAAM2 expression and improvements in remyelination in Guillain- Barre syndrome, suggesting that IFNγ may activate specific pathways redirecting the process." (PMID 32511247, 2020).
hemorrhagic fever (4 papers, 2014 to 2018). An infectious disease caused by certain viruses or bacteria that can damage the walls of tiny blood vessels, making them leak, and can hamper the blood's ability to clot and cause severe, life-threatening illness. "However, pathological cytokine responses including IFNγ, IL-6, IL-10, TNFα, and IP-10, all of which are elevated in AB6 mice during fatal Ang71 infection, have been implicated in inducing vascular permeability with the onset of hemorrhagic fever after infection with the related Dengue virus (DENV)." (PMID 27463517, 2016).
Hepatomegaly (4 papers, 2010 to 2019). Abnormally increased size of the liver. "Lmr15 carried by CcS-16 did not influence parasite load, but controls hepatomegaly and IFNγ in serum." (PMID 31231359, 2019).
Hepatosplenomegaly (4 papers, 2009 to 2026). Simultaneous enlargement of the liver and spleen. "Circulating levels of the classical markers of an inflammatory response, TNFα and IFNγ, may not have been significantly associated with hepatosplenomegaly as they have short-range activity within the tissues of the liver and spleen." (PMID 19149774, 2009).
herpes simplex encephalitis (4 papers, 2014 to 2024). Herpes simplex virus encephalitis (HSE) is caused by the infection of the central nervous system by Herpes simplex virus (HSV) that could have a devastating clinical course and a potentially fatal outcome particularly with delay or lack of treatment. "Classic examples of this are Mendelian susceptibility to mycobacterial disease (MSMD), which results from impaired IFNγ-mediated immunity following exposure to mycobacterial species, and herpes simplex virus encephalitis (HSE) resulting from impaired TLR3-mediated anti-HSV1 immunity." (PMID 33598806, 2021).
IgG4-related disease (4 papers, 2018 to 2025). "Our results suggested the profibrotic cytokines TGFB1, IL1B and IFNG induce fibrosis and that Tregs might produce some of these cytokines in IgG4-related thymitis as well as in the other affected lesions of IgG4-related disease." (PMID 29439708, 2018). "Currently, fibrosis of IgG4-related disease is thought to be induced by profibrotic cytokines such as transforming growth factor beta 1 (TGFB1), interleukin 1 beta (IL1B) and interferon gamma (IFNG), which are secreted by regulatory T cells (Tregs) and CD4-positive cytotoxic T cells." (PMID 29439708, 2018).
interstitial lung disease (4 papers, 2018 to 2024). A diverse group of lung diseases that affect the lung parenchyma. "In addition, increased Eotaxin, IL10, IP10, and MCP1 are found in anti-MDA5 patients with interstitial lung disease; In patients with rapidly progressive interstitial lung disease (RP-ILD), IFNγ, IL1β and IL12 levels are considerably elevated." (PMID 35517781, 2022).
intestinal tuberculosis (4 papers, 2020 to 2025). A tuberculosis that involves the intestine. "Latest molecular-based diagnostic modalities such as GeneXpert, interferon-gamma (IFN-γ) release assays (IGRA), polymerase chain reaction (PCR), multiplex-PCR, and immunological markers are expected to help diagnose intestinal tuberculosis." (PMID 35227196, 2022). "Although the inflammatory polyps in the present case are atypical, the presence of erosions with a ring-shaped tendency suggests that intestinal tuberculosis was a relevant differential, and interferon-gamma-releasing assay, mucosal culture, etc. should have been considered." (PMID 38407743, 2024). "Medical interviews and findings on physical examination, chest X-ray, or chest computed tomography (CT); interferon-gamma release testing (QuantiFERON, T-SPOT), and Mantoux testing are used for the differential diagnosis of intestinal tuberculosis." (PMID 32377946, 2020).
intra-amniotic infection (4 papers, 2020 to 2023). "An elevated level of cytokines IL-1β, IL-6, TNFα, IFNγ, EGF, MIP3α in patients with PROM and intra-amniotic infection." (PMID 34745106, 2021).